TFF3 (trefoil factor 3)
Diseases named in the same sentence as TFF3 in open-access papers (continued):
Sharing a sentence is not in itself a finding about the gene and the disease.
Barrett’s oesophagus (18 papers, 2014 to 2025). "The Cytosponge is a non-endoscopic cell-collection device, which, coupled with a laboratory test for the biomarker trefoil factor 3 (TFF3), can be used to diagnose intestinal metaplasia, which is a hallmark of Barrett’s oesophagus." (PMID 36627580, 2023). "For example, cytosponge‐trefoil factor 3 (TFF3) has been validated for its acceptability, safety, and accuracy in detecting Barrett's esophagus, and recommended by the British Society of Gastroenterology (BSG) as a routine screening test in primary care." (PMID 39856802, 2025). "The Cytosponge is a cell-collection device, which, coupled with a test for trefoil factor 3 (TFF3), can be used to diagnose Barrett’s oesophagus, a precursor condition to oesophageal adenocarcinoma." (PMID 36627580, 2023). "In a recent randomized controlled study in primary care (BEST3 trial), Cytosponge-TFF3 led to a 10-fold increase in the diagnosis of Barrett’s esophagus (BE) among patients with reflux symptoms." (PMID 34358719, 2022). "The VGG16 model showed strong adaptability, with an AUC = 0.88 with respect to detection of patients with Barrett’s oesophagus in TFF3-stained biopsies." (PMID 35954443, 2022). "Although the numbers were small, the offer of Cytosponge-TFF3 led to an increased detection of early neoplasia (dysplastic Barrett esophagus or stage I cancer) compared with the control arm (9 vs." (PMID 34195582, 2021). "In patients with gastro-oesophageal reflux, the offer of Cytosponge-TFF3 testing results in improved detection of Barrett's oesophagus." (PMID 32738955, 2020). "In this multicentre, pragmatic, randomised controlled trial we found that an invitation to have a Cytosponge-TFF3 test led to increased diagnosis of Barrett's oesophagus when compared with usual care by general practitioners." (PMID 32738955, 2020). "The test comprises a non-endoscopic cell collection device coupled with an in vitro test for the specific biomarker, trefoil factor 3 (TFF3), that identifies intestinal metaplasia (the histopathological hallmark of Barrett's oesophagus)." (PMID 32738955, 2020). "The prevalence of Barrett's oesophagus or cancer in the 221 participants who received an endoscopy after testing positive for TFF3 was 59% (n=131)." (PMID 32738955, 2020). "One diagnosis of Barrett's oesophagus in a patient who had a positive Cytosponge-TFF3 test result was omitted from the results, as a coded diagnosis was not identified by any of these data collection methods." (PMID 32738955, 2020). "We have developed a non-endoscopic tool: the Cytosponge, which when combined with trefoil factor 3 immunohistochemistry, can diagnose Barrett’s oesophagus." (PMID 29084829, 2018). "Monoclonal antibodies raised against the TFF3 protein detected TFF3 by immunohistochemistry in oesophageal submucosal glands, intestinal goblet and neuroendocrine cells, Barrett's metaplasia and intestinal metaplasia." (PMID 25900183, 2015). "The BEST3 trial demonstrated the efficacy and safety of the Cytosponge-trefoil factor 3, a cell collection device coupled with the biomarker trefoil factor 3, as a tool for detecting Barrett’s oesophagus, a precursor of oesophageal adenocarcinoma (OAC), in primary care." (PMID 35393308, 2022). "Other methods for the detection of pre-cancerous lesions (i.e., Barrett’s oesophagus) have been investigated, including the use of cytosponge to detect Trefoil Factor 3 (TFF3), which was assessed in a large trial of patients with gastro-oesophageal reflux disease." (PMID 36291888, 2022). "The presence of goblet cells with overexpression of TFF3 is a key feature of Barrett’s oesophagus." (PMID 35954443, 2022). "Randomised controlled trial data from the BEST3 trial has shown that an offer of Cytosponge-TFF3 in the primary care setting in England to individuals on medication for acid reflux increases detection of Barrett esophagus 10-fold over a year compared with standard care." (PMID 34195582, 2021).
Barrett’s oesophagus (continued). "Among 1654 participants in the intervention group who swallowed the Cytosponge device successfully, 221 (13%) underwent endoscopy after testing positive for TFF3 and 131 (8%, corresponding to 59% of those having an endoscopy) were diagnosed with Barrett's oesophagus or cancer." (PMID 32738955, 2020). "Before undergoing endoscopy, the study participants swallowed a Cytosponge so that the researchers could evaluate the safety, acceptability, and accuracy of the Cytosponge-TFF3 test for the diagnosis of Barrett's esophagus compared with endoscopy." (PMID 25634542, 2015). "In recent years, esophageal sponge cytology combined with biomarkers, like TFF3, tissue factor pathway inhibitor 2 (TFPI2), vav guanine nucleotide exchange factor 3 (VAV3), and microRNA, have been validated to have high efficiencies in detecting Barrett's esophagus and associated adenocarcinoma." (PMID 39856802, 2025). "We aimed to 1) assess whether quantitative TFF3 scores can distinguish clinically relevant Barrett's oesophagus (BO) (C≥1 or M≥3) from focal IM pathologies (C<1, M<3 or IM of gastro-oesophageal junction); 2) whether TFF3 counts can be automated to inform clinical practice." (PMID 35843173, 2022). "The Cytosponge-TFF3 test might, therefore, provide a simple, inexpensive way to identify those patients with reflux symptoms who warrant endoscopy to diagnose Barrett's esophagus, although randomized controlled trials of the test are needed before its routine clinical implementation." (PMID 25634542, 2015). "A non-endoscopic oesophageal cell collection device known as the Cytosponge, coupled with a biomarker test for trefoil factor 3 (TFF3), has been shown to increase detection of Barrett's oesophagus ten times over the current standard of care." (PMID 35030332, 2022). "The Cytosponge-trefoil factor 3 (TFF3) is a non-endoscopic test for Barrett esophagus, a precursor of esophageal adenocarcinoma." (PMID 34195582, 2021). "Trefoil Factor 3 (TFF3) has been used in the cytosponge device providing presence or absence of Barrett’s oesophagus with good affect." (PMID 32495144, 2020). "The Cytosponge-trefoil factor 3 (TFF3) test is a novel non-endoscopic cell collection device coupled with an immunohistochemical biomarker that can diagnose Barrett's oesophagus in the primary care setting." (PMID 32738955, 2020). "In this cohort, 21.5% were ≤1 cm and 42.2% were ≤3 cm; of these, the proportion who were TFF3-negative were 65.9% and 55.9%, respectively, suggesting they may have very focal IM that was not sampled or may not qualify for a diagnosis of Barrett’s oesophagus." (PMID 37220898, 2023). "The Cytosponge-trefoil factor 3 (TFF3) is a non-endoscopic test for Barrett's oesophagus." (PMID 32738955, 2020). "In this case–control study, the researchers investigate whether a cell sampling device called the Cytosponge coupled with immunohistochemical staining for Trefoil Factor 3 (TFF3, a biomarker of Barrett's esophagus) can be used to identify individuals who warrant endoscopic investigation." (PMID 25634542, 2015). "Randomised controlled trial data from the BEST3 study has shown that offering a novel non-endoscopic test, the Cytosponge-trefoil factor 3 (TFF3), in the primary care setting in England can diagnose ten times more Barrett esophagus than usual care over a year." (PMID 34195582, 2021).
hepatocellular carcinoma (10 papers, 2014 to 2021). A malignant tumor that arises from hepatocytes. "The forced expression of TFF3 was observed to promote activation of AKT in hepatocellular carcinoma cells, while inhibition of AKT abrogated TFF3-mediated increase in oncogenicity and chemoresistance of hepatocellular carcinoma cells." (PMID 31685806, 2019). "TFF3 has previously been reported to activate AKT in hepatocellular carcinoma cells." (PMID 31658702, 2019). "Very recently, TFF3 was found to be expressed by hepatocellular carcinoma progenitors." (PMID 25222179, 2014). "Recent studies have shown that TFF3 promotes CSC-like behavior in mammary and hepatocellular carcinoma cells, consistent with the current study in lung ADC." (PMID 31685806, 2019).
inflammatory bowel disease (10 papers, 2009 to 2023). A spectrum of small and large bowel inflammatory diseases of unknown etiology. "In this regard, recent studies in animals and pediatric patients with inflammatory bowel disease have shown elevated serum levels of TFF3, an event associated with increased intestinal permeability and inflammation that is not seen in healthy subjects or patients in remission." (PMID 37892398, 2023). "TFF3 has been associated with inflammatory bowel disease (IBD) pathogenesis and is considered as a potential treatment target." (PMID 37299399, 2023). "Several lines of evidence indicate that TFF-3 is a protective factor in the intestinal epithelium and plays a beneficial role in inflammatory bowel diseases in humans." (PMID 26042740, 2015). "DMBT1 was strongly up regulated in inflammatory bowel disease such as UC and DC, in epithelial cells adjacent to the TFF3-producing goblet cells." (PMID 23691218, 2013). "Elevated serum levels of TFF3 have been reported in inflammatory bowel disease and ulceration of the upper gastrointestinal tract." (PMID 19402886, 2009). "Oral administration of TFF3 expressing Lactococcus lactis successfully prevented and healed acute colitis in mice, which opens the possibility to achieve exposure levels sufficient to treat metabolic or inflammatory bowel diseases in humans." (PMID 26083576, 2015). "This implies a role for DMBT1 and TFF3 together in inflammatory bowel disease." (PMID 23691218, 2013). "In addition, miR-7-5p was reported to target TFF3 in inflammatory bowel disease." (PMID 30424721, 2018).
lymph node metastasis (10 papers, 2013 to 2023). "TFF3 has been proposed as an independent risk factor contributing to lymphovascular invasion and lymph node metastasis in BC." (PMID 32652877, 2020). "TFF3 protein expression was positively associated with larger tumour size, lymph node metastasis, higher stage, and poor survival outcome." (PMID 25266665, 2014). "In addition, TFF3 over-expression was the second highest risk next to lymph node metastasis for postoperative survival." (PMID 24358147, 2013). "It has also been found that CTCs tending toward bone metastases express a higher level of trefoil factor 3 (TFF3) than either lymph node metastases or primary tumors." (PMID 38129401, 2023). "In the present study, out of the 16 cases that had high TFF3 mRNA concentration, we found 12 cases (75%) had lymph node metastases." (PMID 29977293, 2018). "Age, lymph node metastasis, and TFF3 and TACC1 over-expression were significantly correlated with low survival (P<0.05, P<0.05, P = 0.005 and P = 0.009, respectively)." (PMID 24358147, 2013). "Multivariate analysis showed that lymph node metastasis and TFF3 and TACC1 over-expression were independent prognostic factors." (PMID 24358147, 2013). "Univariate analyses showed that age, lymph node metastasis, TFF3 over-expression and TACC1 over-expression were significantly correlated with a short survival time." (PMID 24358147, 2013). "Multivariate analysis showed that lymph node metastasis and the expression of TFF3 and TACC1 in tumor epithelial cells were independent prognostic factors for overall survival, and that the hazard ratio (HR) of tumor-related death increased by 3.409 fold in FF3 group (P<0.001; 95% CI 2.387–8.143)." (PMID 24358147, 2013). "It was also found that the expression level of TFF3 in cases with lymph node metastasis was significantly lower than that in the non-lymph node metastasis group." (PMID 34567204, 2021). "TFF3 expression in GC correlates with the occurrences of lymph node metastasis, muscularis propria invasion (≥T2), worse TNM stage, and histological type, which indicates that TFF3 may be an adverse factor in GC progression and metastasis." (PMID 34830815, 2021). "TFF3 was significantly higher in patients with positive lymph node metastasis than that in patients with negative lymph node metastasis (TFF3, 0.61 vs. 0.39; p<0.05)." (PMID 24358147, 2013). "TFF3 expression was significantly higher in patients with positive lymph node metastasis than that in patients with negative lymph node metastasis." (PMID 24358147, 2013). "For example, TFF3 over-expression was detected in approximately 50% of the patients with positive lymph node metastasis vs. one-third in patients with negative lymph node metastasis, indicating that TFF3 over-expression plays an important role in lymph node metastasis in GC patients." (PMID 24358147, 2013).
thyroid cancer (10 papers, 2012 to 2025). "Trefoil factor 3 (TFF3) has been shown to inhibit the migration of thyroid cancer cells while promoting apoptosis, suggesting a dual role in both limiting cancer spread and inducing cell death." (PMID 40346322, 2025). "In thyroid cancer, low expression of TFF3 can increase cell proliferation, migration, and invasion via activation of the IL-6/JAK/STAT3 signaling pathway." (PMID 38745021, 2024). "Another supporting finding is that FCGBP in thyroid cancer can functionally synergize with TFF3 through genetic co-expression, and thus contributing to poor survival in thyroid cancer patients with low TFF3 level." (PMID 35626334, 2022). "Here, we showed that low expression level of TFF3 in thyroid cancer is related to thyroid cancer nodal metastasis." (PMID 34567204, 2021). "TFF3 level in thyroid cancer nodal metastasis tissues was prominently downregulated compared with that in the normal tissues, and the level of TFF3 in thyroid cancer nodal metastasis N0 was overexpressed compared with that in nodal metastasis N1 (P < 0.01)." (PMID 34567204, 2021). "With the continuous development of molecular biology, we can further understand the relationship between TFF3 and the occurrence and development of the thyroid, which is conducive to the early diagnosis and treatment of thyroid cancer." (PMID 34567204, 2021). "We are now focusing on using the understanding of TFF3 function in the development of thyroid cancer to focus on providing new ideas and prospects for early diagnosis and clinical prevention of thyroid cancer." (PMID 34567204, 2021). "The results of this study indicated that TFF3 inhibited the motility of thyroid cancer cells and promoted cell apoptosis." (PMID 34567204, 2021). "Then, we observed high level of TFF3 in normal tissues and low expression of TFF3 in the tissues of thyroid cancer stage 1, stage 2, stage 3, and stage 4 (P < 0.01)." (PMID 34567204, 2021). "Downregulated expression of TFF3 increases the expression of pSTAT3/STAT3, suggesting that the effect of TFF3 expression level on the occurrence of thyroid cancer is closely related to the expression of STAT3." (PMID 34567204, 2021). "To clarify the mechanism by which TFF3 inhibits the progression of thyroid cancer cells, we performed GSEA pathway analysis." (PMID 34567204, 2021). "In summary, the TFF3 detection of thyroid cancer is helpful to evaluate the invasion and metastasis of thyroid cancer and provides a reference for the clinical treatment and prognosis of thyroid cancer." (PMID 34567204, 2021). "In fact, in many types of solid tumors an increase of TFF3 expression level was observed, while in all thyroid cancers of follicular cell origin its expression was decreased when in normal thyroid it was highly expressed." (PMID 28923001, 2017). "Contrarily, only 2 proteins, trefoil factor 3 and sulfotransferase are addressed in thyroid cancer." (PMID 37101287, 2023). "The IL-6/JAK/STAT3 signaling pathway might be involved in the effect of TFF3 on thyroid cancer cell progression." (PMID 34567204, 2021). "The expression level of TFF3 in thyroid cancer was lower than that in normal thyroid tissue." (PMID 34567204, 2021). "In this study, the aim was to explore the role of TFF3 in thyroid cancer." (PMID 34567204, 2021). "Furthermore, GSEA pathway analysis and western blot were used to explore the mechanism by which TFF3 represses the progression of thyroid cancer cells." (PMID 34567204, 2021). "TFF3 inhibits thyroid cancer cell progression related to IL-6/JAK/STAT3 signaling pathway." (PMID 34567204, 2021). "In a previous pilot study we demonstrated that six recently identified marker genes (ADM3/HGD1/LGALS3/PLAB/TFF3/TG) can be successfully applied for a molecular discrimination of benign and malignant thyroid tumours including follicular thyroid neoplasia using surgically removed tissue samples." (PMID 22223087, 2012).
thyroid cancer (continued). "Some the poor prognosis genes identified, such as TFF3 and CDH16, represent well-established thyroid cancer markers." (PMID 27633254, 2016). "In addition to TFF3, other markers such as homogentisate 1,2-dioxygenase (HGD1) and ADM3, a member of the adrenomedullin family, are also recognized for their involvement in thyroid cancer biology, albeit with less clarity regarding their specific roles." (PMID 40346322, 2025).